TKT (transketolase)
Diseases named in the same sentence as TKT in open-access papers (continued):
Sharing a sentence is not in itself a finding about the gene and the disease.
leukemia (7 papers, 2014 to 2025). A malignant (clonal) hematologic disorder, involving hematopoietic stem cells and characterized by the presence of primitive or atypical myeloid or lymphoid cells in the bone marrow and the blood. "Furthermore, others demonstrated that siRNA knockdown of TKTL1 in cultured human leukemia cells caused a significant decrease in TKT activity that was measured by glyceraldehyde-3-P production in the two-substrate X5P and ribose-5-P reaction." (PMID 30646877, 2019). "Fermented wheat germ extract has anti-leukemia activity on the Jurkat cell line through the inhibition of glucose-6-phosphate dehydrogenase (G6PDH) and transketolase enzymes, charging to regulate carbon flux in the glycolytic and pentose pathway, respectively." (PMID 40333775, 2025). "In leukemia, MND1 interacted with other proteins such as TKT to regulate tumor progression, and it modulated chemotherapy sensitivity by PI3K/AKT signaling pathway." (PMID 41424711, 2025). "Transduction of human THP-1 leukemia cells with a lentiviral vector expressing a TKTL1-specific shRNA (THP-1KD) specifically downregulated TKTL1 but not TKT (changed by 4.0 ± 1.2%; n = 3; p = NS)." (PMID 27391434, 2016). "Increased expression of transketolase (TKT) and its isoform transketolase-like-1 (TKTL1) has been related to the malignant leukemia phenotype through promoting an increase in the non-oxidative branch of the pentose phosphate pathway (PPP)." (PMID 35408935, 2022).
liver cancer (7 papers, 2018 to 2023). An epithelial or non-epithelial malignant neoplasm that arises from the liver. "In our previous studies, we found that the incidence of liver cancer was decreased in liver-specific TKT knockout mice compared with control littermates." (PMID 35110545, 2022). "The results showed that TKT is transported to the nuclei of liver cancer cells by interacting with the signal transducer and activator of transcription-1 (STAT-1)." (PMID 33520706, 2020). "TKT has a high positive expression rate in HCC tissues, and TKT enhances the proliferation, migration, invasion and colony formation ability of liver cancer cells." (PMID 33520706, 2020). "Here, using an Fbxl6 knock-in mouse model and HCC patient tissues, we demonstrate the crucial roles of FBXL6 in liver cancer development and show by example that blocking TKT would be sufficient to impede HCC development in a subset of HCC patients with high FBXL6 expression." (PMID 37653031, 2023). "Our previous study indicate that TKT could promote the development of liver cancer by affecting bile acid metabolism." (PMID 35110545, 2022). "TKT then inhibits the expression of the farnesoid receptor (FXR) (a tumor suppressor gene) by promoting the binding of histone deacetylase-3 (HDAC-3) to the FXR promoter, causing increases in intrahepatic bile acid (related to the occurrence of liver cancer)." (PMID 33520706, 2020). "However, the roles of TKT in the initiation of liver cancer are still obscure." (PMID 31949131, 2020). "However, the role of TKT in the initiation of liver cancer is still obscure." (PMID 31949131, 2020). "Furthermore, our previous research also confirms that TKT transports into the nuclear to inhibit FXR promoter activity, affects liver bile acid metabolism, and promotes liver cancer." (PMID 35110545, 2022).
lung adenocarcinoma (7 papers, 2006 to 2025). A carcinoma that arises from the lung and is characterized by the presence of malignant glandular epithelial cells. "High TKT expression is also associated with advanced tumor stage and TKT inhibitors promote apoptosis of lung adenocarcinoma cells and cell cycle blockade." (PMID 36909892, 2023). "NRF2-regulated PPP genes, including G6PD, PGD, TKT, and TALDO1 were first identified in lung adenocarcinoma A549 cells." (PMID 33859744, 2021). "Two of five gastric carcinomas and two of five lung adenocarcinomas had greater than 10-fold overexpression of TKTL1, whereas TKT expression was unchanged in all tested carcinoma tissues (not shown)." (PMID 16465194, 2006). "eIF3i, HSC71, MHC class I antigen, transketolase, citrate synthase, Rab-37, MLH1 and AGR2 might be putative biomarkers in HSP90 inhibition response in lung adenocarcinoma." (PMID 31370342, 2019). "Although emerging evidence has suggested a strong link between the pentose phosphate pathway (PPP) and cancer, the role of transketolase (TKT), an enzyme in the nonoxidative branch of the PPP that connects PPP and glycolysis, remains obscure in Lung adenocarcinoma (LUAD)." (PMID 35711845, 2022).
Hyperglycemia (5 papers, 2012 to 2024). An increased concentration of glucose in the blood. "At first, we assumed that allithiamine is able to enhance the transketolase activity, resulting in a decreased flux of hyperglycaemia-induced pathologic pathways involving the polyol, AGEs, PKC, and hexosamine pathways, similar to thiamine and benfothiamine." (PMID 32517031, 2020). "It has been shown that expression of TKT is a critical factor in preventing hyperglycemia-induced metabolic dysfunction in vitro." (PMID 25806370, 2015). "Collectively, our data suggest that allithiamine could alleviate the hyperglycaemia-induced endothelial dysfunction due to its potent antioxidant and anti-inflammatory effect by a mechanism unrelated to the transketolase activity." (PMID 32517031, 2020). "Transketolase (TKT), one of the key enzymes in the PPP, was increased after exposure to hyperglycaemia, indicating its active role in the hyperglycaemia-induced reactions." (PMID 35624805, 2022).
melanoma (5 papers, 2016 to 2024). A malignant, usually aggressive tumor composed of atypical, neoplastic melanocytes. "This gene codes for a homodimeric transketolase, generally overexpressed in cancer cells for the acquisition of a glycolytic phenotype (the Warburg effect); in melanoma, it was proved to be regulated by methylation in vitro." (PMID 39202425, 2024). "In melanoma cells and head and neck cancer cells, DNA hypomethylation of the TKT L1 gene promoter increases TKT L1 expression and activity, promoting HIF1-α accumulation and stability and inducing the Warburg effect." (PMID 34631530, 2021). "Elevated TKT expression levels were reported in melanoma as well in lung, breast and prostate cancer cells." (PMID 32528879, 2020). "Another important enzyme in the PPP, playing a pivotal role in melanoma proliferation and progression, is the transketolase (TKT)." (PMID 32528879, 2020). "More specifically, exposure to UVA augments the proliferation of melanoma cells, by increasing the expression levels of TKT in melanoma." (PMID 32528879, 2020). "Our data suggests that we cannot rule out the possibility that TKT acts in concert with TKTL1 as we observed that TKT is highly expressed in melanoma cell lines and knockdown of TKTL1 impacts TKT expression, if only modestly." (PMID 26907172, 2016).
endometritis (4 papers, 2023 to 2025). An acute or chronic, usually bacterial infectious process affecting the endometrium. "Compared to resistant cows, endometritis-affected cows produced considerably more of the genes TLR4, LITAF, TNF-α, TKT, RPIA, TLR7, TNF-α, TKT, and AMPD1." (PMID 39195794, 2024). "Gene expression levels were considerably higher in endometritis-affected cows than in resistant ones for the genes TLR4, TLR7, TNF-α, NCF4, LITAF, OXSR1, TKT, RPIA, and AMPD1." (PMID 37368756, 2023). "The expression levels of the genes TLR4, TLR7, TNF-α, NCF4, LITAF, OXSR1, TKT, RPIA, and AMPD1 were significantly greater in endometritis-affected Holstein dairy cows than in resistant ones." (PMID 37368756, 2023). "The immune (TLR4, TLR7, TNF-α, IL10, NCF4, and LITAF), antioxidant (ATOX1, GST, and OXSR1), and erythritol-related (TKT, RPIA, and AMPD1) genes in endometritis-affected and healthy Holstein dairy cows were characterized in this research using a PCR-DNA sequencing technique." (PMID 37368756, 2023). "Molecular genetic analyses of the immunological (TLR4, TLR7, TNF-α, IL10, NCF4, and LITAF), antioxidant (ATOX1, GST, and OXSR1), and erythritol-related (TKT, RPIA, and AMPD1) genes comparing healthy and endometritis cows found differences in nucleotide sequence and transcript levels." (PMID 37368756, 2023). "Single nucleotide variants (SNPs) in the genes were discovered using PCR-DNA sequencing for immune (TLR4, TLR7, TNF-α, IL10, NCF4, and LITAF), antioxidant (ATOX1, GST, and OXSR1), and erythritol-related (TKT, RPIA, and AMPD1) genes found in resistant and endometritis-infected Holstein dairy cows." (PMID 37368756, 2023). "Nucleotide sequence variations between healthy and endometritis-affected cows were revealed using PCR-DNA sequencing for immune (TLR4, TLR7, TNF-α, IL10, NCF4, and LITAF), antioxidant (ATOX1, GST, and OXSR1), and erythritol-related (TKT, RPIA, and AMPD1) genes were reported by44." (PMID 38459095, 2024). "Nucleotide sequence variations between healthy and endometritis-affected cows were revealed using PCR-DNA sequencing for immune (TLR4, TLR7, TNF-α, IL10, NCF4, and LITAF), antioxidant (ATOX1, GST, and OXSR1), and erythritol-related (TKT, RPIA, and AMPD1) genes." (PMID 37368756, 2023).
head and neck squamous cell carcinoma (4 papers, 2022 to 2025). A squamous cell carcinoma that arises from any of the following anatomic sites: lip and oral cavity, nasal cavity, paranasal sinuses, pharynx, larynx, and salivary glands. "Although few studies have further confirmed that PPP is enhanced in OSCC, three independent studies have demonstrated that transketolase (another PPP enzyme) is overexpressed in head and neck squamous cell carcinoma (HNSCC) cell lines and tissues." (PMID 35327590, 2022). "Glucose-6-phosphate dehydrogenase (G6PD) is a key regulator of NADPH production; overexpression of G6PD/TKT downstream of NRF2–MYC drives nucleotide biosynthesis and progression in head and neck squamous cell carcinoma (HNSCC)." (PMID 41470226, 2025). "In this metabolic pathway, glucose-6-phosphate dehydrogenase (G6PD) and transketolase (TKT) are key downstream effectors driven by NRF2, contributing to the progression of head and neck squamous cell carcinoma." (PMID 38650924, 2024).
malaria (4 papers, 2015 to 2023). Malaria is a serious and sometimes fatal disease caused by a parasite that commonly infects a certain type of mosquito which feeds on humans. "Here, we compare the assessment of thiamin status by direct measurement of TDP using HPLC against erythrocyte transketolase assays in these malaria patients." (PMID 32996449, 2020). "Another docking study using AutoDock Vina was conducted to recognise the probable inhibitor against transketolase enzyme in Plasmodium falciparum, the protozoan responsible for malaria." (PMID 27071308, 2016).
neuroblastoma (4 papers, 2013 to 2023). Neuroblastoma (NB) is the most common solid, extracranial childhood tumor. "The PPP pathway in neuroblastomas is upregulated by CO, including 6-phosphogluconate dehydrogenase (PGDH) from the oxidative branch of the PPP and transketolase (TKT) from the non-oxidative branch of the PPP." (PMID 31500396, 2019).
beriberi (3 papers, 2011 to 2017). Beriberi is a condition that occurs in people who are deficient in thiamine (vitamin B1). "The period of intensive research on infantile beriberi occurred before the invention of the erythrocyte transketolase activity (ETK) assay and there have been very few investigations of infantile beriberi in the last 40 years." (PMID 21364976, 2011). "A cohort of 778 sick infants admitted during one year without clinical evidence of beriberi were studied prospectively and erythrocyte transketolase assays (ETK) performed." (PMID 21423705, 2011). "We therefore recruited 778 sick infants admitted during one year at Mahosot Hospital, Vientiane, without clinical evidence of beriberi, and performed erythrocyte transketolase (ETK) assays." (PMID 21423705, 2011).
head and neck cancer (3 papers, 2021 to 2022). A primary or metastatic malignant neoplasm affecting the head and neck. "C-myc-directed NRF2 drives the malignant progression of head and neck cancer through the activation of glucose-6-phosphate dehydrogenase and transketolase." (PMID 35770119, 2022). "Furthermore, G6PD- and TKT-regulated nucleotide biosynthesis is more important than redox regulation for maintaining the malignant features of head and neck cancer." (PMID 33859744, 2021). "Taken together, these data support the potential for use of the NRF2/G6PD/TKT gene signature as a prognostic biomarker and for the development of NRF2-targeted therapies that alter cellular metabolism as novel and promising treatment options for head and neck cancer." (PMID 33859744, 2021).
non-small cell lung carcinoma (3 papers, 2017 to 2025). A group of at least three distinct histological types of lung cancer, including non-small cell squamous cell carcinoma, adenocarcinoma, and large cell carcinoma. "In the non-small cell lung cancer model the following 5 DEPs were found to be involved in the GSH metabolism pathway (G6PD, PRDX2, IDH1, MGST1 and 6PGD), 4 DEPs in the PPP pathway (G6PD, TALDO1, TKT and 6PGD) and 1 DEP involved in the glycolysis pathway (ALDH3A1)." (PMID 28303926, 2017).
tuberculosis (3 papers, 2012 to 2023). A chronic, recurrent infection caused by the bacterium Mycobacterium tuberculosis. "The transketolase (TKT) enzyme in Mycobacterium tuberculosisrepresents a novel drug target for tuberculosis treatment and has low homologywith the orthologous human enzyme." (PMID 22645655, 2012). "In whole blood samples, TKT transcript was significantly increased in patients with sepsis [iFigure/GSE13015], malaria infection [iFigure/GSE34404] compared to uninfected controls, and in active pulmonary tuberculosis (TB) compared to latent TB [iFigure/GSE19442]." (PMID 31415630, 2019).
Wernicke-Korsakoff syndrome (3 papers, 2003 to 2023). Wernicke-Korsakoff syndrome is a brain disorder, due to thiamine deficiency that has been associated with both Wernicke's encephalopathy and Korsakoff syndrome. "In another study, researchers studied transketolase activity in alcoholic men without Korsakoff ’s psychosis and their sons who had not yet been exposed to alcohol (i.e., who were alcohol naive) and compared it with transketolase activity in nonalcoholic volunteers and their sons." (PMID 15303623, 2003). "Also, TKT, a multifunctional protein in the non-oxidative branch of the pentose phosphate pathway, seems to be related to some neurological disorders such as AD, PD, and Wernicke-Korsakoff syndrome, and reduced levels of TKT have been found in the substantia nigra of PD patients." (PMID 37095366, 2023). "One study compared the activity of transketolase, PDH, and α-KGDH derived from skin cells of people with and without Korsakoff ’s psychosis." (PMID 15303623, 2003).
breast tumor (2 papers, 2017 to 2021). "Phosphorylated SRC-3 transcriptionally upregulates transketolase expression to promote breast tumor growth and metastasis to the lung." (PMID 33593309, 2021). "The aim of this study was to provide a better understanding of the role of PPP enzymes TKT and G6PD in breast tumors." (PMID 29290982, 2017).
Cognitive impairment (2 papers, 2019 to 2023). Abnormal cognition is characterized by deficits in thinking, reasoning, or remembering. "Seven differentially expressed autoantibodies were recognised as cognitive impairment-related, including HSPD1, CDK19, TKT, BRSK2, NRAS, LMNA, and CAMK2A." (PMID 38107644, 2023). "TKT controlled D-ribose metabolism, and activation of TKT with BTMP decreased D-ribose levels, followed by a reduction in AGE formation, Tau hyperphosphorylation, neuronal death and cognitive impairment." (PMID 31307014, 2019). "Though activation of TKT through BTMP is downstream of the D-ribose pathway, which may not be direct evidence, the current work at least showed that a decrease in D-ribose levels could help the amelioration of cognitive impairment." (PMID 31307014, 2019).
colitis (2 papers, 2021). Inflammation of the colon. "To further investigate the mechanism underlying TKT deficiency-induced colitis, we performed RNA sequencing (RNA-seq) using the colonic tissues of 4-week-old WT and TKT∆IEC mice." (PMID 34535624, 2021). "In the present study, we show that TKT deficiency in the intestinal epithelium results in reduction of glycolytic metabolites and insufficient ATP production, which can lead to epithelial cell apoptosis, intestinal barrier defects, spontaneous colitis and mouse growth retardation." (PMID 34535624, 2021). "Furthermore, lack of transketolase-like 1 (TKTL1), which belongs to the TKT gene family, aggravates murine experimental colitis." (PMID 34535624, 2021). "For example, transketolase (TKT), a key player in the glycolysis and non-oxidative PPP (Pentose Phosphate Pathway), maintains intestinal ATP production and inhibits apoptosis-induced colitis in mice." (PMID 35008842, 2021).
colorectal tumor (2 papers, 2015 to 2024). "Proteins that regulate glycolysis (PGK1, PGAM1, ENO1, PKM, TKT), ammonia detoxification (GLUD1), and other metabolic pathways (LDHA, GAPDH, MDH2) were reported to be differentially expressed in mouse xenograft colorectal tumor models with different radio- responsiveness." (PMID 38410100, 2024).
COVID-19 (2 papers, 2021). A disease caused by infection with severe acute respiratory syndrome coronavirus 2. "In module 2, mono-CD14+ cells in patients with severe COVID-19 exhibited higher expression levels of glycolysis-related genes (LDHA and PKM) and PPP-related genes (PGD and TKT), which may be involved in the proinflammatory response (upregulation of S100A8, S100A9, S100A12, and IL1B)." (PMID 33936072, 2021).
diabetic retinopathy (2 papers, 2008 to 2021). "Thiamine helps transketolase in removing toxic metabolites, counteracting high glucose-induced damage in microvascular cells, and progression of diabetic retinopathy/nephropathy in diabetic animals." (PMID 33916491, 2021). "This suggestion lends support from the finding, that the administration of benfotiamine (an analogon of the cofactor thiamine and transketolase activator) blocks hyperglycaemic damage and prevents experimental diabetic retinopathy in mice." (PMID 19812737, 2008).
Encephalopathy (2 papers, 2019 to 2020). Encephalopathy is a term that means brain disease, damage, or malfunction. "Mutations in NDUFA11 cause severe neurodegenerative phenotypes such as brain atrophy and encephalopathy, and mutations in TKT cause diseases associated with neurological phenotypes." (PMID 32004313, 2020). "Transketolase (TKT) was demonstrated to be an important enzyme in regulating D-ribose metabolism in T1DM-related encephalopathy rats." (PMID 31307014, 2019).
esophageal cancer (2 papers, 2024 to 2025). A primary or metastatic malignant neoplasm involving the esophagus. "Esophageal cancer tissues in HMGA1 conditional knock-in (HMGA1KI/KIK14-cre+) mice displayed a much higher proportion of TKT-positive cells as compared with those in esophageal cancers induced in control mice (HMGA1KI/KI)." (PMID 39080260, 2024). "To further validate the regulatory role of HMGA1 in the expression of TKT, we detected TKT in esophageal cancer in HMGA1 conditional knock-in (HMGA1KI/KIK14-cre+) mice." (PMID 39080260, 2024). "Results from IHC also showed that TKT was more strongly expressed in esophageal carcinomas than that in adjacent normal esophageal epithelial tissues both in human and in mice." (PMID 39080260, 2024). "In addition, the functional outcome of TKT upregulation in cancer remains to be elusive although TKT is reported to be highly expressed in esophageal cancer." (PMID 39080260, 2024).
esophageal squamous cell carcinoma (2 papers, 2024). Esophageal squamous cell carcinoma (ESCC) is a type of esophageal carcinoma (EC) that can affect any part of the esophagus, but is usually located in the upper or middle third. "TKT is also highly expressed in esophageal squamous cell carcinoma, and associated with a poor prognosis." (PMID 38434975, 2024).